RNU6-293P (RNA, U6 small nuclear 293, pseudogene)
Gene: Small nuclear RNA gene on chromosome 6 (158,926,466 to 158,926,571, reverse strand). Ensembl gene ENSG00000223191.
Homologues: Orthologues: chimpanzee U6 (100% identical), macaque U6 (91% identical), dog U6 (54% identical), pig U6 (54% identical), mouse Gm23641 (53% identical), mouse Gm55875 (52% identical). Paralogues in human: RNU6-364P (64% identical), RNU6-283P (63% identical), RNU6-621P (63% identical), RNU6-1075P (62% identical), RNU6-1091P (62% identical), RNU6-1249P (62% identical), RNU6-403P (62% identical), RNU6-737P (62% identical), RNU6-797P (62% identical), RNU6-1124P (61% identical), RNU6-144P (61% identical), RNU6-181P (61% identical), and 1283 more.